CD44 (CD44 molecule (IN blood group))
Diseases named in the same sentence as CD44 in open-access papers (continued):
Sharing a sentence is not in itself a finding about the gene and the disease.
tumor (continued). "We therefore considered CD44 as a suitable surrogate parameter when tracking tumor cells in vivo." (PMID 23385555, 2013). "Therefore we took CD44 positivity as a cancer stem cell marker and confirmed the tumor sphere formation, cell invasion to define cancer stem cell phenotype." (PMID 24386318, 2013). "The CD44+/CD24− tumor cells from the MD-231 cell line were sorted by flow cytometry." (PMID 23760650, 2013). "If the clonal hypothesis had been correct, the tumor would have been comprised of only CD44-positive cells." (PMID 23908856, 2013). "Notably, while spheres generated from single CD44+CD24neg cells contained only cells of like phenotype, all of 18 CD44+CD24neg cell-derived tumours showed a minor CD24low+component (mean 3.7 ± 0.7% cells)." (PMID 23982961, 2013). "First, the expression of the CD44 surface marker varies greatly from one tumor to another." (PMID 24019906, 2013). "In 47 (24.4%) cases, ALDH/CD44 co-expressing cells were detected, including 27 (57.4%) showing only a few scattered co-expressing cells (low abundance) and 20 (42.6%) cases that showed large aggregates or confluent sheets of such tumor cells (high abundance)." (PMID 24091605, 2013). "Therefore, we cannot exclude the possibility of a cell-type specific effect of CD44 down-regulation on tumor and metastasis formation." (PMID 23565227, 2013). "Binding of HA to CD44 plays roles in cell adhesion, immune responses, and tumor development." (PMID 24363762, 2013). "Thus, the shedding of CD44 can have important effects on tumor cell behavior; however, its effects on orasphere formation or stemness have not been explored." (PMID 24403253, 2013). "However, recently the role of CD44-expression in solid neoplasms as a tumour marker for stem cells is discussed and controversial." (PMID 23419168, 2013). "CD44 is a surface molecule which mediates cell adhesion and migration by binding extracellular matrix components such as hyaluronic acid, osteopontin, or activating receptor tyrosine kinases, which are related with tumor progression and metastasis." (PMID 23902592, 2013). "Only CD44+CD24low+-generated tumours responded to RO4929097." (PMID 23982961, 2013). "Moreover, further information on the in vivo distribution of HA conjugated nanocarries as well as their tumor localization should be useful to design new anticancer therapies based on CD44 targeting." (PMID 23533773, 2013). "The expression of CD44 and CD133 decreased and, to our surprise, human-specific endothelial-associated marker CD34 increased in the tumor nodules." (PMID 24280306, 2013). "Similarly, when analyzed separately for HPVDNA+ and HPVDNA− tumors, in the multivariate analyses adjusted for sex, stage, age, and tumor site, CD44 expression was still correlated to a favorable DFS and OS for the HPVDNA+ group, but not the HPVDNA− group." (PMID 24156023, 2013). "Interestingly, nuclear Ki67 immunostaining of proliferating tumor cells on primary tumor and lung paraffin sections showed a specific structure of primary tumors and lung metastases in mice bearing tumors depleted of CD44." (PMID 23565227, 2013). "However, double knockdown tumors were about 30% (shRb-1/shCD44–2E) or 20% (shRb-2/shCD44–3E) lighter than Rb knockdown alone, suggesting that CD44 suppression has a strong impact on tumor growth in the context of Rb suppression." (PMID 24324613, 2013). "The observed reduction, and reduced variation between tumours, of CD44-positive staining after enzymatic dissociation may be of particular significance for studies that aim to use CD44-positive staining as a prognostic indicator." (PMID 23437366, 2013). "The mice injected with the 5 × 104 CD44+CD117+CSCs with lentivirus miR-200c showed much higher tumor free rates than the mice injected with the 5 × 104 CD44+CD117+CSCs with lentivirus mock or 5 × 104 CD44+CD117+CSCs without lentivirus infection on different days after the injection." (PMID 23842108, 2013).
tumor (continued). "CD44+/CD24− tumor cells from the MD-231 cell line were sorted by flow cytometry." (PMID 23760650, 2013). "Tumours derived from CD44+CD24low+cells (n = 18) were comprised of both cell phenotypes with a mean of 32 ± 4% CD24low+ cells and a majority CD24neg cells (as observed in spheres seeded from single CD44+CD24low+cells)." (PMID 23982961, 2013). "It is noteworthy that the purity of the sorted CD24neg cells was only 96% at innoculation, thus the 4% CD24low+ cells contaminating the sorted CD44+CD24neg may have generated CD24low+ cells in the CD44+CD24neg tumours." (PMID 23982961, 2013). "In addition to a small in tumor size, CD44 knockdown K562 cells showed a significant reduction in tumor outgrowth after subcutaneous injection when compared with control K562 cells." (PMID 24257075, 2013). "LYVE-1 was hypothesized to have an effect that is similar to CD44 on blood endothelial cells, which is facilitated by interacting with tumor cell surface HA and influences tumor cell adhesion." (PMID 23717428, 2013). "The abrogation of tumour growth resulting from CD44 inhibition, either in vivo or in vitro, indicates its functional significance and differential patterns of expression of CD44 isoforms can similarly affect cellular properties." (PMID 23437366, 2013). "Thus, we analyzed how CSE affects the distribution of specific cell surface markers that are associated with tumor initiation and self renewal, specifically ALDH1 activity, high CD44/low CD24, CD49f and CD133." (PMID 23919753, 2013). "In tumor biology, evidence has accumulated that metastasis in different types of cancer is directly or inversely related to the expression of CD44 gene products, depending on the expression pattern of CD44 isoforms and on the organ of origin." (PMID 23565227, 2013). "In addition to having tumor-initiating properties, the CD44+/MyD88+ subtype of EOC cells express multiple pluripotency-associated genes, can differentiate into vascular tumor progenitors and, in addition, undergo EMT to yield migratory mesenchymal CSCs." (PMID 24403249, 2013). "However, a recent study showed that CD44− cells form spheres, possess tumor-initiating capability, and are chemoresistant, like CD44+ cells." (PMID 23626764, 2013). "Moreover, in addition to these micrometastases we identified larger growing metastases, composed by 40-50 CD44+ tumor cells adjacent to blood vessels of human origin." (PMID 23951338, 2013). "However, our current data also showed that CD44+/CD24+ cells formed tumor xenografts in two of six mice after the injection of 1×105 cells." (PMID 23799994, 2013). "PH provoked a significantly greater CD44 expression in tumor-bearing livers (p < 0.03)." (PMID 23385555, 2013). "There is evidence that tumor cells which express CD44 and CD24, exhibit a stem-cell-like behavior." (PMID 23419168, 2013). "Thus the anti-angiogenic protein, FKBPL, and AD-01, offer a promising and alternative approach for targeting both CD44 positive tumours and vasculature networks." (PMID 23457460, 2013). "This interesting observation suggests that CD44hi cells may be exposed to inhibitory influences towards tumor growth by cells that have a lower intensity surface CD44 expression in the same tumor population." (PMID 24019906, 2013). "Moreover, surface CD44 expression varies greatly between individual tumors; the tumor cells that most highly label for surface CD44 seem to possess greater competence at tumor formation." (PMID 24019906, 2013). "Tumor cells that express CD44 and CD24 exhibit a stem-cell-like behavior." (PMID 23419168, 2013). "In addition, cells were analyzed by FACS for cell surface proteins which differentiate luminal versus basal/myoepithelial cells (EPCAM/CD49f) and cancer cells with tumor initiating capabilities (CD44/CD24)." (PMID 23879992, 2013). "Furthermore, LLL12 also suppresses the SUM-159 ALDH+/CD44+/CD24− cell growth in a mouse xenograft tumor model." (PMID 24376586, 2013).
tumor (continued). "Interestingly, xenografts generated from sorted CD44+CD24neg DT-22 cells consistently contained 2–8% CD44+CD24low cells in all of 18 tumours, raising the possibility of a niche-induced inter-conversion in vivo." (PMID 23982961, 2013). "In addition, CD24/CD44 staining of the established tumor cell lines MCF-7 (Luminal ER+, PR+, HER2-), T47D (Luminal ER+, PR+, HER2-) and MDA-MB-231 (Basal ER-, PR-, HER2-) indicated these cells had one main population." (PMID 23879992, 2013). "Notably, while tumours generated from sorted CD44+CD24low+ DT-22 cells comprised both phenotypes, tumours arising from sorted CD44+CD24neg cells were almost entirely CD44+CD24neg." (PMID 23982961, 2013). "HA cables may have the same capacity to activate LYVE-1 as their capacity to activate CD44 in vivo, and our results as well as the findings of previous reports showed that some tumor surfaces contain high levels of HA." (PMID 23717428, 2013). "Relapsed tumor cells show CD44+CD24- phenotype with higher rates of tumorigenesis, in vivo." (PMID 24324806, 2013). "We also observed that some tumor cells were both CD44+ and CD24+." (PMID 24167614, 2013). "However, there is discrepancy around the data on the role of CD44 and its isoforms in tumour biology." (PMID 23342032, 2013). "CD44, on the other hand, was previously speculated to be involved in tumor metastasis involving adhesion molecules between cells." (PMID 23426065, 2013). "For each number injected, CD44+CD24low+ cells generated tumours with shorter latency." (PMID 23982961, 2013). "Since we did observe CD44 on the surface of the tumor cells during transendothelial migration we asked whether CD44 complexes with MT1-MMP on the leading edge of extravasating cells." (PMID 24194929, 2013). "Additionally, CD44, which is known to promote tumor cell motility and invasion, can anchor active MMP-9 to the cell surface, and has been localized with MMP-9 and MT1-MMP on cellular invadipodia." (PMID 24194929, 2013). "In addition, CD44(+) population isolated from xenograft human tumour and cell lines displayed high tumour initiating ability and metastasis in vitro." (PMID 23936768, 2013). "The same effect was demonstrated during cell isolation from fresh tumour specimens, in which commonly used methods of enzymatic cell dissociation caused a reduction in cell staining for CD44 when compared with a non-enzymatic dissociation method." (PMID 23437366, 2013). "In tissue sections, some tumor cells were CD44+ and others were CD24+." (PMID 24167614, 2013). "So we next sought to investigate whether β-catenin participated in CD44-mediated tumor cell proliferation." (PMID 24257075, 2013). "However, making use of an orthotopic xenograft OS mouse model, we demonstrated that reduced CD44 expression facilitated primary tumor growth and formation of pulmonary metastases." (PMID 23565227, 2013). "For tumours of epithelial origin, including those of the head and neck, breast, prostate and colon, isolation of CSCs has frequently been based on their greater cell-surface expression of CD44." (PMID 23437366, 2013). "Additionally, expression of different isoforms of CD44 has been related to poor prognosis in a number of different tumor types, and studies in animal models have provided evidence for a functional role of CD44 isoforms in metastasis." (PMID 22916191, 2012). "Indeed, in addition to tumorigenic capability, expression of cell surface CD44 and the ability to form tumor-spheres are two intrinsic markers of cancer stem-like cells." (PMID 22679501, 2012). "Together these observations suggest that a better understanding of how CD44 interacts with HA is required to explain the relevance of these complex interactions to tumor progression and metastasis, which in turn will identify new routes for therapeutic intervention." (PMID 22916191, 2012).
tumor (continued). "CD44 interacts with osteopontin and regulates its cellular functions leading to tumour progression." (PMID 22693526, 2012). "DNA content analysis of the cytokeratin+ CD44+/CD90+ tumor population, a subset shown to be highly tumorigenic in other epithelial cancers, revealed an imatinib-mediated right-shift in DNA profile consistent with the expansion of early S-phase cells and cell cycle arrest (bottom right)." (PMID 23285214, 2012). "Similarly with the relation with DFS, the proportion of CD44+/CD24-/low tumor cells (P = 0.001), basal-like feature (P = 0.029), and TNM stage (P = 0.027) were strongly correlated with OS." (PMID 22762532, 2012). "It should be noted that CSC were able to undergo asymmetric division also in vivo because after injection in mice, they both produced differentiated cells that constituted the bulk of the tumor and self-renewed themselves as demonstrated by the presence of CD44+CD24− cells in all excised tumors." (PMID 22328933, 2012). "SP and MP cells found to strongly express tumor metastasis marker CD44." (PMID 22272227, 2012). "This raises the possibility that Rac1 activation upon HA/CD44/Rac1 engagement may trigger intracellular signals that induce CD44 cleavage and enhance tumour cell migration/invasion." (PMID 22363471, 2012). "The fact that despite the accelerated radiotherapy regimen applied in this study, CD44 remained a predictor of local relapse, suggests that reduced radiosensitvity may characterise this tumour sub-population." (PMID 22333601, 2012). "With FACS analysis, this decrease in tumor volume with chemotherapy was associated with a non-statistically significant increase in TICs as measured by CD44+/CD24−, ALDH+, and MSFE." (PMID 22879872, 2012). "The molecular imaging-detected higher CD44 expression in hypoxic tumor regions in vivo and ex vivo could be due to hypoxia driving up CD44 expression, or due to hypoxic environments attracting CD44 expressing cells." (PMID 22937154, 2012). "Recently, CD44 has recently attracted considerable attention in tumor biology." (PMID 22482084, 2012). "CD44 is an adhesion molecule for extracellular matrix components such as hyaluronic acid and osteopontin, and plays an important role not only in wound healing and cell migration, but also in tumor invasion and metastasis." (PMID 23031740, 2012). "Two of these markers, CD44 and Tenascin C, which are expressed in the stem cell niches of normal brains, are expressed at much higher levels in the perivascular niche where tumor stem cells are proposed to reside." (PMID 22393407, 2012). "Cell adhesion molecules such as CD44 or L1-CAM may be involved in the migration of tumor cells and the cleavage events are required for L1- or CD44-dependent cell migration." (PMID 23251384, 2012). "CD44+/CD24−/line- tumor cells (CSC) from clinical specimens were sorted using flow cytometry." (PMID 23056395, 2012). "CD44+/CD24- tumor cells were detected in 70.1% of the tumors, with a median proportion of 5.8%." (PMID 22762532, 2012). "In the breast, cells positive for the epithelial lineage marker cytokeratin, CD90 and CD44 may identify epithelial ductal progenitor cells as well as clonogenic tumor cells." (PMID 23285214, 2012). "Conversely, the CD44−/CD24+ cells were usually found in the central portion of the tumours." (PMID 23028444, 2012). "Furthermore, different cells of a tumour can express various, possibly different sets of CD44 isoforms." (PMID 23151220, 2012). "On this basis, we explored also the possibility of alternative splicing of CD44 in several cell lines for the head and neck region, including normal, immortalized and tumor-derived lines, the latter including previously uncharacterized derivatives from matched pairs of normal and metastatic tissue." (PMID 22242150, 2012). "Furthermore, the tumor xenografts seeded by cells from the CD44+CD24−/low: Lineage− fraction comprised the same cellular heterogeneity observed in the original tumor." (PMID 22470504, 2012).
tumor (continued). "In addition, the level of CD44 and Sca1 expression in the grafted tumors was comparable with that in the grafts of CD44+ tumor cells." (PMID 22277639, 2012). "At this time point, CD44-KD and CD147-KD xenografts both showed significantly reduced tumor weights compared to control groups (789±192 mg for PC-3M-luc-CD44-KD and 892±238 mg for PC-3M-luc-CD147-KD versus 1369±117 mg for PC-3M-luc and 1376±250 mg for PC-3M-luc-scr, respectively)." (PMID 22870202, 2012). "CD44 alternative splicing is related to neoplasia and metastasis in many cancers." (PMID 22242150, 2012). "Furthermore we studied the effect of GSI treatment on Notch downstream target Hes1 and tumor initiating cell markers CD44 and EpCAM in sorted CD44+/EpCAM+ cells." (PMID 23094026, 2012). "This could also serve as groundwork for the future development of new drug targets that may inhibit hyaluronan/CD44-mediated tumor metastasis and cancer progression." (PMID 22400115, 2012). "For this reason, we focused on the change in tumor expression of CD44 as a result of chemotherapy." (PMID 23031740, 2012). "We used this fingerprint to track the changes of CD44 expression during tumour progression." (PMID 23151220, 2012). "They showed that tumors arising from CD44+ cells reproduced the original tumor heterogeneity and could be serially passaged, suggesting that CD44+ cells were stem cells, as they had the properties of differentiation and self-renewal." (PMID 22384257, 2012). "The CD44 transmembrane glycoproteins play multifaceted roles in tumor progression and metastasis." (PMID 22937154, 2012). "A strong correlation was found between the percentage of CD44+/CD24− cells in primary tumours and distant metastasis development (p = 0.0001); in addition, there was an inverse significant association with ER and PGR status (p = 0.002 and p = 0.001, respectively)." (PMID 23028444, 2012). "Upregulated expression of CD44 increases tumour growth and has an anti-apoptotic effect." (PMID 22433494, 2012). "This may strongly support the interconversion of CD44 phenotype during tumourigenesis, indicating the differential expression of markers in tumours." (PMID 22693526, 2012). "In summary, CD44+CD24+ESA+ cells did support a more efficient virus replication and the higher virus titer caused more rapid tumor elimination in nude mice with CD44+CD24+ESA+ cells derived tumor xenografts." (PMID 22901246, 2012). "The regulatory interaction of CD44 in signalling pathways in tumour cells remains unresolved." (PMID 22693526, 2012). "In fact, pretreatment levels of CD44 and its variants have been correlated with TNM staging and may well be able to serve as tumour markers in head and neck cancers." (PMID 23125850, 2012). "It thus contributes to tumor progression by enhancing tumor-promoting properties of CD44." (PMID 22216413, 2012). "In addition, the positive correlation of CD44 with metastasis was also demonstrated in prostate CSCs, which showed that cells with enhanced clonogenic, tumor-initiating and metastatic capacities were enriched in the CD44+ cell population." (PMID 22895640, 2012). "It is possible that one or more CD44 members may impart adverse cellular characteristics, potentially through activation of erbB or other receptors, onto tumour cells whilst other members may have a neutral or even tumour inhibitory role." (PMID 23039365, 2012). "Besides, CD44 also plays an indispensable role in tumor pathology, involved in cell differentiation, invasion and metastasis." (PMID 22788972, 2012). "The expression of CD44 may have contributed to the greater stroma diameters and lower tumour radii measured for the infiltrative subtypes in our study." (PMID 22405101, 2012). "Moreover, expression pattern of CD44 isoforms was found to be stable, meaning that colorectal type expression profile remained unchanged from tumour cell suspensions (in vitro) throughout primary and metastatic colon cancer xenografts." (PMID 23151220, 2012).